THBS1 (thrombospondin 1)
Diseases named in the same sentence as THBS1 in open-access papers (continued):
Sharing a sentence is not in itself a finding about the gene and the disease.
cancer (continued). "In contrast to LAMB1, THBS1 has previously been shown to play a role in SCC and other cancers." (PMID 31580518, 2019). "Similarly, THBS1 has been shown enhance EMT and promote cancer spreading." (PMID 34439128, 2021). "The development of the Proclarix 5‐parameter biomarker model (herein referred to as biomarker model) incorporating THBS1, CTSD, tPSA, %fPSA and age was performed on all 955 samples to calculate specificity, NPV and PPV at a fixed sensitivity of 90% to identify significant cancer." (PMID 35474911, 2020). "However, other studies have revealed that THBS1 promotes EMT transition and cancer cell invasion." (PMID 27634890, 2016). "However, as a subgroup of CSC, L3 does not express genes related to cancer dormancy (FN1, CD47, and THBS1); therefore, L3 is a smaller, independent cluster that expresses high levels of stem cell markers while lacking the expression of cancer dormancy marker genes." (PMID 37858183, 2023). "Besides, WTAP regulates the expression of certain genes related to motility of cancer cells, such as chemokine ligand 2 (CCL2), chemokine ligand 3 (CCL3), matrix metallopeptidase 3 (MMP3), lysyl oxidase-like 1 (LOXL1), hyaluronan synthase 1 (HAS1), and thrombospondin 1 (THBS1)." (PMID 30062093, 2018). "Moreover, secreted factors (for example, thrombospondin 1 (THBS1) and biglycan (BGN)), and growth factors and cytokines (for example, TGFβ, CXCL12/SDF1, CTGF and FGF2), many of which actively control endothelial and cancer cell behaviour, were differentially regulated between iNFs and iCAFs." (PMID 28198360, 2017).
infection (50 papers, 2008 to 2026). The state of being infected such as from the introduction of a foreign agent such as serum, vaccine, antigenic substance or organism. "Thbs1 deficiency leads to unchecked protease activity, worsened lung damage, and increased mortality in some infection models." (PMID 41488667, 2025). "Furthermore, THBS1 has been shown to enhance the susceptibility of Gram-positive bacteria to infection by other researchers." (PMID 39431015, 2024). "The receiver operating characteristic (ROC) curve showed that protein kinase C-binding protein NELL2, thrombospondin-1, and complement factor I have diagnostic potential for differentiating staphylococci and streptococci intramammary infection and inflammation." (PMID 37889706, 2023). "In severe infections or tissue damage, dysregulated Thbs1 can contribute to neutrophil hyperactivation and tissue injury." (PMID 41488667, 2025). "The mRNA level of DNMT3b in HuH-7 cells was decreased by infection of lentivirus expressing sh-DNMT3b (p < 0.05), while that of THBS1 in HuH-7 cells infected with lentivirus expressing oe-THBS1 was increased (p < 0.05)." (PMID 31847842, 2019). "The duplicated copies of integrin alpha 2 (ITGA2) on ssa01 and ssa13 as well as copies of thrombospondin-1 (THBS1) on the homeologous segments of ssa01 and ssa09 showed significant up-regulation during the second infection." (PMID 30873203, 2019). "BMMΦ from obese and lean mice produced more comparable amounts of Thbs1 protein after 24 h infection, with a slight overproduction still observed in obese mice." (PMID 23922979, 2013). "Western blot analysis demonstrated that BMMΦ from obese mice produced much more Thbs1 and Arg1 proteins after 4 h infection compared with BMMΦ from lean mice." (PMID 23922979, 2013). "The up-regulation of host THBS1 expression by T. cruzi to facilitate the infection of human cells represents an additional mechanism that contributes to the pathogenesis of T. cruzi infection." (PMID 23133440, 2012). "THBS1 is required for the infection process of T. cruzi as evidenced by RNAi of that specific isoform." (PMID 23133440, 2012). "The roles of the members of the THBS1 sub-network in the infection process are also being investigated fully by our group in this section." (PMID 23133440, 2012). "Pre-exposure of recombinant NTSP or THBS1 to T. cruzi significantly enhanced cellular infection of wild-type mouse embryo fibroblasts (MEF) compared to the C-terminal domain of THBS1, E3T3C1." (PMID 23133440, 2012). "Infective trypomastigotes up-regulate the expression of laminin γ-1 (LAMC1) and thrombospondin (THBS1) to facilitate the recruitment of trypomastigotes to enhance cellular infection." (PMID 23133440, 2012). "The elucidation of T. cruzi surface molecules that interact with THBS1 to enhance cellular infection will advance our understanding of the molecular pathogenesis of T. cruzi infection." (PMID 23133440, 2012). "Very recently our group characterized a novel THBS1 interaction with T. cruzi that enhances cellular infection." (PMID 23133440, 2012). "The result of this analysis showed that the only ECM proteins, LAMC1 and THBS1, were important in the early infection process." (PMID 23133440, 2012). "Thbs-1 (NM_011580) was up-regulated in the lungs of mice at day 6 post infection, compared to uninfected animals." (PMID 18483551, 2008). "In the immune and infection context, THBS1 and its receptor, CD47, inhibit T cell differentiation." (PMID 36481664, 2022). "The ECM-receptor interaction pathway may contribute to the involvement of TM infection in various cellular activities through regulating the expression of many proteins, such as THBS1." (PMID 30598657, 2018). "However, the mechanisms by which THBS1 is up-regulated by the parasite to modulate cellular infection are not completely known." (PMID 23133440, 2012).
infection (continued). "Furthermore, knockdown of THBS1 rendered mammalian cells less susceptible to cellular infection by T. cruzi indicating that THBS1 also plays an important role in the process of cellular infection by T. cruzi." (PMID 23133440, 2012). "Importantly, intratracheal transfer of IL-10+/+ CD11b+Ly6G+Ly6C+ cells 1 day before infection to Thbs1-/- mice restored their ability to produce IL-10 in the lungs, improved host defense, and reduced lung inflammation and permeability upon infection." (PMID 41733356, 2026). "The expression of thrombospondin 1 (THBS1), which has been linked to the inhibition of neovascularization and tumorigenesis (THBS1 thrombospondin 1 [Homo sapiens (human)] - Gene - NCBI (nih.gov)), was upregulated in piglets receiving ineffective infection treatment." (PMID 40995220, 2025). "As the progenitor subset, proCAFs are likely the first to be influenced by infection, acquiring immunomodulatory features such as ZFP36- and THBS1-mediated regulation that promote immune escape in the early stages of tumorigenesis." (PMID 41194113, 2025). "For example, TcCalr binds to thrombospondin 1 (TSP-1) expressed on the surface of embryo fibroblasts and enhances trypomastigote infection of these cells." (PMID 36993959, 2023). "During the process of cellular infection, the parasite induces host cells, to increase the levels of host thrombospondin-1 (TSP-1), to facilitate the process of infection." (PMID 32664627, 2020). "We observed that host THBS1 and parasite surface TcCRT are important for MEF cellular infection by T. cruzi." (PMID 23133440, 2012). "Taken together, these findings indicate that THBS1 interacts with TcCRT on the surface of T. cruzi through the NTSP domain and that this interaction enhances cellular infection." (PMID 23133440, 2012). "In order to explore the significance of host THBS1 and TcCRT in cellular infection by T. cruzi, our group used THBS1 KO MEF and WT MEF in infection assays." (PMID 23133440, 2012). "Taken together, these findings indicate that THBS1 interacts with TcCRT on the surface of T. cruzi through the NTSP domain and that this interaction enhances cellular infection by T. cruzi." (PMID 23133440, 2012). "DK212 infection substantially repressed CD36, THBS1, and SERPINA1 expression, which might prevent the maturation of immature dendritic cells." (PMID 36059479, 2022). "Notably, the upregulated genes included S100A7, THBS1, Myosin, and TUBA, which were involved in the immune and infection response." (PMID 35311085, 2022). "Levels of Thbs1 and Arg1 in uninfected BMMΦ were comparable to the ones in BMMΦ after 1 h infection (data not shown)." (PMID 23922979, 2013). "The late emergence of State 6, marked by apoptotic signaling genes (THBS1, IL1R2, S100A8), suggested that ASFV may eventually trigger cell death in heavily infected macrophages, potentially contributing to the cytopathic effects observed in advanced infection." (PMID 40723441, 2025). "Myeloid dendritic cells in dormant infections also showed notable differences in mRNA expression, affecting neutrophil recruitment (C1QA, C1QB, ITGAM), immune checkpoint regulation (IFITM2, IFITM3, CST7, THBS1), and T-cell response (VISIG4, V-set immunoglobulin domain containing 4)." (PMID 39563367, 2024). "The platelet aggregation protein thrombospondin 1, which was up-regulated 2.2-fold in our microarray data, indicates that the thrombogenic response induced by S100A8/A9 in endothelium may have been activated following HPS infection." (PMID 19196461, 2009).
cardiovascular disease (18 papers, 2013 to 2025). "THBS1 level dramatically elevates under hypoxia and is implicated in several cardiovascular disorders." (PMID 36675257, 2023). "Therefore, THBS1 may be an important molecular component associated with high-salt diet-induced cardiovascular disease by activating its downstream target TGF-β." (PMID 33250683, 2020). "Tenascin-C (TnC) and thrombospondin-1 (TSP-1) are involved in the pathogenesis of cardiovascular disease." (PMID 41010873, 2025). "Both thrombospondin-1 and thrombospondin-2, however, have been studied in cardiovascular disease and mediate atherosclerotic plaque development in mice." (PMID 37944753, 2023). "In some AngII-induced cardiovascular disease models, the expression level of THBS1 was significantly increased." (PMID 35211156, 2022). "We noticed that six DEPs (Pltp, Pir, Thbs1, Tmem70, Hacd2, and Ppm1k) closely related to cardiovascular disease were either significantly downregulated or upregulated." (PMID 36312255, 2022). "The functions of markedly induced levels of THBS1 are confirmed within the tumor microenvironment and in cardiovascular disorders." (PMID 34575042, 2021). "Increasing the understanding of the role of Thbs1 in cardiovascular diseases may provide new directions for the treatment of cardiovascular diseases." (PMID 35811717, 2022). "Pre-operative Thrombospondin 1 expression was also associated with survival after lower extremity revascularization and long-term cardiovascular events when evaluated in independent cohorts of non-surgical patients with cardiovascular disease." (PMID 35468922, 2022). "Thrombospondin-1 (THBS1) levels elevate under hypoxia and have relevance in several cardiovascular disorders." (PMID 34575042, 2021). "We predicted 6 candidate genes (PANK1, TRIB1, BMPR2, HDAC9, THBS1, and LARP1) that might bind to miR-942-5p and played a role in cardiovascular disease." (PMID 33869307, 2021). "It belongs to the Thrombospondin family, which is known to play an important role in cardiovascular diseases, although THBS1 is the best-known member and THBS2 itself has not been deeply studied." (PMID 32605321, 2020). "THBS1 is the first member of the THBS gene family, which plays a significant role in many biological processes related to the occurrence and progression of cardiovascular diseases, such as angiogenesis, inflammation, and tissue remodeling (Zhao, Isenberg & Popel, 2018)." (PMID 32874785, 2020).
adenocarcinoma (7 papers, 2017 to 2024). A common cancer characterized by the presence of malignant glandular cells. "Three proteins, namely, ITGB1, FBN1, and THBS1, were identified as common across the examined adenocarcinomas, DCIS and BC of all grades." (PMID 36010848, 2022). "Four top performing EV-associated proteins that distinguished adenocarcinoma cases from controls, SRGN, TPM3, THBS1 and HUWE1, yielded a combined area under the receiver operating characteristic curve (AUC) of 0.90 (95% CI = 0.76-1)." (PMID 29221141, 2017). "The PDE4DIP (Phosphodiesterase 4D Interacting Protein) that anchors phosphodiesterase in centrosomes was shown to co-express with the endogenous tumor suppressor gene THBS1, and high expression levels of PDE4DIP were associated with improved survival rates in adenocarcinoma patients." (PMID 36552904, 2022). "Finally, could serological detection of proteins such as ITGB1, FBN1, and THBS1 be employed as a general screening tool for adenocarcinomas ?" (PMID 36010848, 2022). "Importantly, a THBS1 threshold of 7 ng/ml serum could correctly categorize 17/18 (94%) tested samples as adenocarcinomas and 4/6 CRPC-NE (67%) samples as those with therapy-induced NED." (PMID 33859239, 2021).
heart disease (5 papers, 2017 to 2024). "However, Thbs3 is unique in that it functions opposite to Thbs1, Thbs2, and Thbs4, where it enhances cardiac pathology with disease stimulation, while mice deficient in Thbs3−/− were partially protected from cardiac disease." (PMID 30622267, 2019). "To recapitulate the induction of Thbs1 during heart disease we generated cardiomyocyte-restricted transgenic mice overexpressing Thbs1 using an inducible α-myosin heavy chain (αMHC) promoter system." (PMID 34168130, 2021). "Five of these genes codes for proteins that are known to be involved in heart disease and three of these, COL12A1, THBS1 and HSP70 are of particular interest." (PMID 32878883, 2020).
kidney disease (4 papers, 2022 to 2025). "THBS1, implicated in tubulointerstitial remodeling and inflammation, and CFHR5, associated with renal disease progression, were significantly upregulated in the FD group." (PMID 41301692, 2025).
lung (4 papers, 2016 to 2024). "We compared gene expression signatures of primary tumors and lung metastatic tumors, and identified Thrombospondin-1 (TSP1) as highly up-regulated in the lung metastatic tumors." (PMID 29100277, 2017).
metabolic disease (4 papers, 2015 to 2022). A congenital disorder (due to inherited enzyme abnormality) or acquired (due to failure of a metabolically important organ) disorder resulting from an abnormal metabolic process. "Our results showed that at the level of the biofunctions related with diseases and disorders, the changes induced by a chronic intake of the LFHCC diet are implicated in cardiovascular and metabolic diseases (TPM, GSN and THBS1)." (PMID 26152126, 2015). "Regrettably, this study did not measure the circulatory level of thrombospondin-1 (TSP1), a natural inhibitor of neovascularization, notably increased in the platelet-poor plasma of aged adults, and those with cardiovascular and metabolic disease." (PMID 32727585, 2020).
infectious disease (3 papers, 2021 to 2025). A disorder directly resulting from the presence and activity of a microbial, viral, or parasitic agent in humans. "This study not only establishes physiologically relevant immuno‐lung organoid models for modeling macrophage‐mediated tissue damage, but also identifies a previous unrecognized role of the THBS1‐(ITGA3+ITGB1) pathway in driving lung cell senescence during infectious disease." (PMID 40712141, 2025). "QCLGF regulated the expression of THBS1 and the KEGG pathways of carbohydrate metabolism, lipid metabolism, signal transduction, the immune system, and infectious disease: bacterial." (PMID 35127552, 2021).
inflammation (3 papers, 2013 to 2024). Aberrant reaction of the microcirculation characterized by movement of fluid and leukocytes from the blood into extravascular tissues. "Thrombospondin-1 (TSP-1) deficiency in mice results in lacrimal gland and corneal inflammation that resembles the human disease." (PMID 24086667, 2013). "THBS1 can regulate inflammatory cytokine secretion and angiogenesis by activating NF-κB, and CTRP9 attenuates atrial inflammation and fibrosis by suppressing the NF-κB and Smad2/3 signaling pathways." (PMID 33414684, 2020).
vascular disorder (3 papers, 2014 to 2024). A general term used to describe any disease affecting blood vessels]. "The evidence presented demonstrates that THBS1 serves as a promising therapeutic target for cancerous malignancies or proliferative vascular disorders." (PMID 39273281, 2024).
bacterial infection (2 papers, 2022 to 2023). "DRAM1 was also in close proximity to FAM49B (related to bacterial infection), THBS1 (related to autophagy), TAGLN2 (related to phagocytosis), and PDIA3 (related to autophagy), which displayed higher expression levels in and around the cell nucleus." (PMID 37919720, 2023). "In particular, we identified that FFAR2+TNFAIP6+ NEUs and THBS1+IL1B+ MOs undertook an important role in the immune response to bacterial infection." (PMID 36119025, 2022).
musculoskeletal system diseases (1 paper, 2025). "THBS1 is also associated with the development of musculoskeletal system diseases." (PMID 40475787, 2025).
THBS1 also shares sentences with these, for which no sentence is quoted: chronic kidney disease (4 papers); systemic sclerosis (4); acute myeloid leukemia (3); cholangiocarcinoma (3); chronic pancreatitis (3); cutaneous melanoma (3); dilated cardiomyopathy (3); esophageal cancer (3); penile squamous cell carcinoma (3); stomach cancer (3); acute respiratory distress syndrome (2); Anxiety (2); benign prostatic hyperplasia (2); chronic atrophic gastritis (2); colon adenocarcinoma (2); E. coli infection (2); esophageal squamous cell carcinoma (2); Ewing sarcoma (2); gastric cardia adenocarcinoma (2); glomerulonephritis (2); hypertrophy (2); Parkinson disease (2); sarcoma (2); Trypanosoma cruzi Infection (2); urothelial carcinoma (2); acute myocardial infarction (1); acute stress disorder (1); alcohol cirrhosis (1); allergic asthma (1); amelanotic melanoma (1).
A further 118 diseases each share a sentence with THBS1 in 1 paper.